RELA (RELA proto-oncogene, NF-kB subunit)
Diseases named in the same sentence as RELA in open-access papers (continued):
Sharing a sentence is not in itself a finding about the gene and the disease.
osteosarcoma (6 papers, 2011 to 2022). A usually aggressive malignant bone-forming mesenchymal neoplasm, predominantly affecting adolescents and young adults. "These authors revealed that the decrease of ACTN4 expression by specific shRNA attenuated the level of phosphorylation of the RelA/p65 subunit of NF-kappaB in osteosarcoma cells." (PMID 31766144, 2019). "Consistent with the phenotypes of osteosarcoma cells, the up‐regulation of RelA, RelB, c‐Rel, and CUL4B in hFOB1.19 cells also led to increased colony formation and increased invasion." (PMID 29377600, 2018). "We observed osteosarcoma cells had increased RelA, RelB, c‐Rel, and CUL4B levels in the cytoplasm and nucleus compared to hFOB1.19 cells, but not p50 and p52." (PMID 29377600, 2018). "RelA, RelB, and c‐Rel mRNA species were significantly up‐regulated in all four osteosarcoma cell lines compared to hFOB1.19 cells, with the highest expression being observed in c‐Rel (~eightfold), and similar effects were observed in RelA and RelB (~sixfold)." (PMID 29377600, 2018). "Given that RelA, RelB, and c‐Rel bind to the promoter region of CUL4B and regulate its expression, thereby causing CUL4B overexpression in osteosarcoma cells, we sought to determine whether the NF‐κB subunits were activated." (PMID 29377600, 2018). "Interestingly, with the increase in tumor malignancy in osteosarcoma patients, the proportion of nuclear translocation of RelA gradually increased." (PMID 29377600, 2018). "Our gene expression results are strongly supported by previous studies, which showed that cell death stimulation with daunorubicin, cisplatin, or p14ARF over-expression in U2OS osteosarcoma cells resulted in RelA mediated transcriptional repression of pro-survival genes, Bcl-xL or XIAP." (PMID 21347231, 2011). "As expected, osteosarcoma cells expressing lower levels of TNFR1, TNFR1 + RelA, TNFR1 + RelB, TNFR1 + c‐RelA, CUL4B, and CUL4B + RelA; SPD304‐treated cells; and p21‐overexpressing cells exhibited dramatically higher percentages of cells in the S phase." (PMID 29377600, 2018). "In addition, we also determined the localization patterns of RelA, RelB, p52, and CUL4B in clinical samples from patient 4, who was diagnosed with osteosarcoma at MSTS stage IV based on the histopathological features." (PMID 29377600, 2018).
pulmonary fibrosis (6 papers, 2015 to 2023). Chronic progressive interstitial lung disorder characterized by the replacement of the lung tissue by connective tissue, leading to progressive dyspnea, respiratory failure, or right heart failure. "In our study, the interaction map identified RELA as a direct target gene of miRNA-21 which has been discussed as a therapeutic target in pulmonary fibrosis." (PMID 32630753, 2020). "IMD‐0354 (an IKKβ inhibitor) prevented the activation of RelA and collagen content in bleomycin‐induced lung fibrosis in mice." (PMID 26337045, 2015). "For pulmonary fibrosis, current studies have shown that the phosphorylation of RELA on Ser536 may be the core regulator of pulmonary fibroblasts." (PMID 35370663, 2022). "By analyzing the target interaction network VCAM1,RELA,CDK2,JUN,CDK1,HSP90AA1,NOS2, SOD1,CASP3,AHSA1, PTGER3 are at the core of the network, which can be regarded as the key targets of Astragalus polysaccharides in treating pulmonary fibrosis." (PMID 35370663, 2022).
sarcoma (6 papers, 2021 to 2024). A usually aggressive malignant neoplasm of the soft tissue or bone. "The results showed that human amino-terminal enhancer of split (AES, a corepressor gene of RELA) RNA expression was markedly elevation, but fused in sarcoma (FUS, a coactivator gene of RELA) RNA expression was suppressed dramatically in the HK2-Six1 cells." (PMID 34513929, 2021). "Mechanistically, we found that this novel intronic circFGFR1int2 promoted FGFR1 expression by recruiting the transcription activators P65 (RELA) and FUS (fused in sarcoma), and by suppressing miR-4687-5p, which was found to be an inhibitor of FGFR1." (PMID 37993879, 2023). "Notably, SIX1 targeted the promoters of the amino-terminal enhancer of split (AES) and fused in sarcoma (FUS), which are cofactors of nuclear factor-κB (NF-κB) subunit RELA, and then inhibited the transactivation function of RELA." (PMID 34513929, 2021).
acute myeloid leukemia (5 papers, 2018 to 2025). Acute myeloid leukemia (AML) is a group of neoplasms arising from precursor cells committed to the myeloid cell-line differentiation. "The antagonistic relationship between RelA and RelB also has disease relevance, as was explored earlier in a discussion on acute myeloid leukemia." (PMID 29874793, 2018). "In addition, the ZMYND8-v-rel reticuloendotheliosis viral oncogene homolog A (avian) (RELA) chimeric transcripts were reported in a four-month-old patient with acute erythroid leukemia, a type of acute myeloid leukemia (AML)." (PMID 33670804, 2021). "The genes contributing the most to the acute myeloid leukemia pathway (RAF1, RELA, and IKBKB) are related with NF-KB signaling, a process already known to also play a role in AD and PD." (PMID 33362460, 2020).
Arthritis (5 papers, 2019 to 2023). Inflammation of a joint. "Pathogenic variants in RELA drive an autosomal dominant inflammatory syndrome marked by mucosal ulceration, fevers, arthritis, gastrointestinal inflammation, and rash, which we have named RAID." (PMID 36926348, 2023). "NR4A2 and RelA proteins were overexpressed in inflamed synovium prior to symptoms of arthritis, suggesting that gene expression changes documented in whole paws were largely driven by elevated expression in diseased synovium." (PMID 35529439, 2022). "Their interdependent activities play a pivotal role in the transformation of FLS in arthritis and in the inflammatory pathology of diverse tissues where RELA and SOX4 are co-expressed." (PMID 35529852, 2022). "In addition, future investigations using a variety of in vivo arthritis models are required to further delineate the molecular and functional interactions of SOXC and RELA proteins during synovial inflammation." (PMID 35529852, 2022). "The functionally redundant activities of Sox4, Sox11 and Sox12 in TNF-induced arthritis and the diverse range of stimuli that can potentially activate the canonical NF-κB signaling in the FLS are suggestive of a role for multiple additional co-factors besides SOXC and RELA." (PMID 35529852, 2022).
B-cell lymphoma (5 papers, 2016 to 2025). "Before analysing the effect of the RelA T505A mutation on B-cell lymphoma progression in the Eμ-Myc model, we first characterised its effects in normal C57Bl/6 mice." (PMID 36240065, 2022). "We therefore decided to investigate the effect of the RelA T505A mutation in a second model of cancer, the Eμ-Myc mouse model of B-cell lymphoma." (PMID 36240065, 2022). "Therefore, since overexpression of MYC is a feature of many types of cancer and results in DNA replication stress leading to genomic instability and tumorigenesis, we next investigated the effect of the RelA T505A mutation in the well-established Eμ-Myc mouse model of B-cell lymphoma." (PMID 36240065, 2022). "We next focused on the expression of 389 NF-κB (RELA) targets recently identified from the genomic analysis of a B-cell lymphoma cell line (BJAB)." (PMID 35455458, 2022). "Using the Eμ-Myc model of B-cell lymphoma, mice mutated at the putative CHK1 T505 phosphosite (T505A) in the RelA transactivation domain, exhibited reduced survival." (PMID 36240065, 2022). "To learn more, about the consequences of the RelA T505A mutation on the DNA replication response in cancer, we decided to investigate its effect in a cancer model driven by the MYC oncogene, the Eμ-Myc model of B-cell lymphoma." (PMID 36240065, 2022).
ependymal tumor (5 papers, 2017 to 2021). A group of neoplasms which arise from the ependymal lining of the cerebral ventricles and from the remnants of the central canal of the spinal cord. "Correlative analyse showed that RELA fusions were significantly related to the higher tumor grade because the most of RELA fusions events (16/17) occurred in grade III ependymal tumors." (PMID 31324163, 2019). "In this study of our single institutional series, the prognostic factors of ependymal tumors included conventional pathological features such as Ki67 index and newly discovered molecular markers including RELA gene fusion and H3K27me3." (PMID 31324163, 2019). "We aimed to demonstrate the significance of histological characteristics, the v-relavian reticuloendotheliosis viral oncogene homolog A (RELA) fusions and other molecular features in ependymal tumors." (PMID 31324163, 2019). "Ependymal tumors were classified into supratentorial RELA positive (ST-EPN-RELA; n = 2), supratentorial YAP1 positive (ST-EPN-YAP; n = 2), posterior fossa type A (PF-EPN-A; n = 1), or posterior fossa type B (PF-EPN-B; n = 1), and one remained unclassified." (PMID 31693904, 2019). "RELA fusions were mostly present in intracranial ependymomas (17/19) and were significantly correlated with the age, tumor grade, cellularity, cellular atypia, necrosis and the Ki67 index in the supratentorial ependymal tumors." (PMID 31324163, 2019). "Thus, IHC is a simple, sensible and reproducible method that permits to detect a pathological activation of the NFκB pathway, which could be used as a surrogate of the RELA fusion in ependymal tumors." (PMID 30325077, 2019).
medulloblastoma (5 papers, 2012 to 2024). A malignant, invasive embryonal neoplasm arising from the cerebellum. "While pathways involved in cell cycle, and DNA repair were up-regulated in medulloblastoma, NFΚB pathway, RELA pathway, Interleukin-2 (IL2), Interleukin-27(IL27) signaling pathways were down-regulated in medulloblastoma compared to healthy cerebellum samples from GTEx." (PMID 36918656, 2023).
oral cancer (5 papers, 2016 to 2025). "Spearman’s correlation analysis revealed a strong positive (p < 0.0001) correlation (r = 0.5980) between hnRNPD and NFκB (RelA) expression in oral cancer tissue." (PMID 35396527, 2022). "Present study, for the first time demonstrate the involvement of transcription factor NFκB (RelA) in transcriptional up regulation of human hnRNPD in oral cancer and suggest the role NFκB (RelA)-hnRNPD axis in oral cancer." (PMID 35396527, 2022). "Conversely, the silencing of NFκB (RelA) gene expression brings about favorable trends in oral cancer cell survival." (PMID 35396527, 2022). "RelA-mediated Becn1 expression was essential for ROS-induced autophagy in oral cancer cells irradiated by laser." (PMID 33425768, 2020). "In this study, we present the following findings: first, LPLI induces ROS production and elevated RelA transcriptional activity in oral cancer cells." (PMID 27632526, 2016). "Therefore, we analyzed the expression of hnRNPD and NFκB (RelA) in clinical specimens from 37 oral cancer patients (N = 37) and oral mucosa from 10 normal subjects by immunohistochemistry." (PMID 35396527, 2022). "Thus, results of the present study for the first time convincingly demonstrate NFκB (RelA) mediated transcriptional upregulation of hnRNPD expression in oral cancer." (PMID 35396527, 2022). "Second, RelA induces BECN1 expression, which induces autophagy in oral cancer cells exposed to LPLI." (PMID 27632526, 2016). "Herein, we found that ROS production is important for the activation of RelA and for BECN1 expression, which in turn induces autophagy in oral cancer cells exposed to LPLI." (PMID 27632526, 2016). "Moreover, the levels of phosphorylated RelA/p65 at Ser536 (RelA S536-P), a primary active component in the canonical NF-κB pathway, and BECN1 expression were elevated in LPLI-treated oral cancer cells." (PMID 27632526, 2016). "Moreover, reactive oxygen species (ROS) production was induced, which increased RelA transcriptional activity and beclin 1 (BECN1) expression in oral cancer cells irradiated with LPLI." (PMID 27632526, 2016). "The specific roles of RelA and BECN1 on the process of autophagy in oral cancer cells irradiated with LPLI remain unclear." (PMID 27632526, 2016). "Knockdown of RelA significantly suppressed the elevation in BECN1 and MAP1LC3 expression and the ratio of MAP1LC3-II/I in the cells exposed to LPLI, suggesting that LPLI may trigger ROS production and activate RelA, thereby turning on BECN1 expression and inducing autophagy in oral cancer cells." (PMID 27632526, 2016).
pneumonia (5 papers, 2014 to 2023). An acute, acute and chronic, or chronic inflammation focally or diffusely affecting the lung parenchyma, caused by an infection in one or both of the lungs (by bacteria, viruses, fungi, or mycoplasma.). "Depleting the hepatic STAT3 and RelA ablated the acute-phase response induction and increased the mortality in a mouse pneumonia model." (PMID 30151394, 2018). "Hepatic STAT-3 and RelA knock out increased the mortality in a mouse pneumonia model." (PMID 30473633, 2018). "By utilizing a relA spoT double mutant, previous studies demonstrated that the stringent response is required for the bacterial virulence in the infection models of Drosophila melanogaster feeding, murine acute pneumonia, murine skin infection, and rat lung agar bead." (PMID 36602339, 2023). "Several recent studies on relA-deleted A. baumannii unveiled a global regulatory role of relA in bacterial adherence, biofilm formation, and Ade multidrug efflux family; as well as a reduced virulence in a Galleria mellonella model and neutropenic murine pneumonia model." (PMID 35231068, 2022).
squamous cell carcinoma (5 papers, 2014 to 2022). A carcinoma arising from squamous epithelial cells. "When tumor area NF-κB scores were examined this way, RelA was found to be expressed at higher levels in men compared with women, in patients aged 65 and over compared with younger ones, and in patients with squamous cell carcinoma compared with adenocarcinoma." (PMID 26147201, 2015). "To comprehensively examine NF-κB expression in NSCLC, we analyzed serial sections of primary tumor samples from 77 well-documented patients (36 adenocarcinomas, 40 squamous cell carcinomas and 3 large cell carcinomas) for immunoreactivity of RelA, RelB, P50, and P52/P100." (PMID 26147201, 2015). "In HPC cell lines (HPCM1 and HPCM2; both squamous cell carcinoma), we observed significant decreases in CD271 expression following transfection with small-interfering (si)RNA targeting RELA, with similar results observed in HSC3 cells (tongue squamous cell carcinoma)." (PMID 36273237, 2022).
triple-negative breast carcinoma (5 papers, 2012 to 2025). An invasive breast carcinoma which is negative for expression of estrogen receptor (ER), progesterone receptor (PR), and human epidermal growth factor receptor 2 (HER2). "This was further supported by a study from our group, which showed that EZH2 and RelA localized to the RelB promoter and supported transcription of RelB in triple-negative breast cancer cells." (PMID 29874793, 2018). "Interestingly, EZH2 was also found to support NF-κB target gene expression in triple-negative breast cancer cells by acting as a coactivator in a complex containing RelA and RelB." (PMID 29874793, 2018). "Thus, NF-κB transcriptionally up-regulates TrkB and NTF3 through direct binding of RelA and NF-κB1 to the regions in the promoters, and this increased transcription is necessary and sufficient for triple negative breast cancer cells to resist anoikis." (PMID 23185507, 2012). "In triple-negative breast cancer, PKC-ι was found to play a critical role in invasiveness via the PKC-ι/RelA signaling pathway." (PMID 40243672, 2025). "BRD4 has also been proven to be a necessary co-activator of the inflammatory transcription process driven by the combination of NF-κB with acetylated RelA, and a necessary co-activator of the diacetylated form of TWIST in triple negative breast cancer." (PMID 37446009, 2023).
acute lymphoblastic leukemia (4 papers, 2008 to 2020). Leukemia with an acute onset, characterized by the presence of lymphoblasts in the bone marrow and the peripheral blood. "Activation of p50 homodimers and p50:RelA heterodimers was detected in all major subtypes of human acute lymphoblastic leukemia (ALL)." (PMID 18596915, 2008). "Indeed, we and others have previously suggested that induction and maintenance of T-cell acute lymphoblastic leukemia (T-ALL), a devastating pediatric blood cancer, depends on the cross talk of three transcription factors, NOTCH1, MYC, and RELA (NF-κB)." (PMID 21356087, 2011).
adenoma (4 papers, 2009 to 2022). A neoplasm arising from the epithelium. "We found that aspirin (at doses resulting in serum salicylate levels relevant to humans (0.5–1.5 mM)) induces phosphorylation and degradation of IκBα, nuclear translocation of RelA and the induction of apoptosis in xenografted HT-29 tumours and in adenomas from Min/+ mice." (PMID 28718829, 2017). "Furthermore, deletion of RelA in intestinal epithelial cells prevents formation of adenomas in the Min/+ model." (PMID 28718829, 2017). "Furthermore, the presence of numerous phosphorylated RelA positive immune- and intestinal epithelial cells were observed in adenomas from Il10−/− mice." (PMID 19551144, 2009).
anaplastic ependymoma (4 papers, 2018 to 2022). Anaplastic ependymoma is a rare, malignant type of ependymoma that most often arises in the supratentorial region of the brain of children and young adults and that manifests with variable symptoms including headaches, nausea, vision impairment, memory loss and difficulty walking. "Recent genomic analyses have indicated that most supratentorial anaplastic ependymomas are associated with fusion events involving RELA or YAP1." (PMID 29440180, 2018).
Autoimmunity (4 papers, 2019 to 2025). The occurrence of an immune reaction against the organism's own cells or tissues. "Although the summary of the clinical manifestations of the patients with RelA deficiency in this study showed that systemic autoinflammation and autoimmunity in RelA dominant-negative were indeed more common than RelA haploinsufficiency." (PMID 40134438, 2025). "For instance, RelA is critical for CD4+ Tconv activation since its deletion prevent the development of autoimmunity in Foxp3CreRelaloxmice." (PMID 31749798, 2019).
bladder cancer (4 papers, 2017 to 2020). "Then, we detected survivin and p65/RelA expression in one normal bladder mucosa tissue and 4 bladder cancer tissues which were diagnosed with bladder urothelial carcinoma staging from pT1 to pT4 by western blot." (PMID 28139689, 2017). "Bladder cancer cell lines exhibited significantly increased survivin and nuclear p65/RelA expression compared to the ureter urothelial cell line." (PMID 28139689, 2017). "Bladder cancer tissue specimens revealed significant upregulated survivin and nuclear RelA expression compared with that of adjacent normal mucosa tissue specimens." (PMID 28139689, 2017). "Furthermore, Pearson’s correlation coefficient analysis suggested a significant positive correlation between expression of survivin and p65/RelA in 40 bladder cancer tissue specimens (R = 0.6708, p < 0.01)." (PMID 28139689, 2017).